IL33 (interleukin 33)
Diseases named in the same sentence as IL33 in open-access papers (continued):
Sharing a sentence is not in itself a finding about the gene and the disease.
asthma (continued). "This study might be an ideal model for assessing the effects of leptin and obesity per se separately in an IL-33-induced asthma model." (PMID 34074279, 2021). "In conclusion, in the Th2 cytokine milieu of asthma, FLG deficient mutation in airway epithelial cells may increase the epithelial permeability and the expression of IL-33/TSLP which positively feedback the Th2 inflammation response." (PMID 34484176, 2021). "We assessed how exogenous leptin influences the IL-33-induced asthma model." (PMID 34074279, 2021). "Therefore, IL-33 is considered a pivotal regulator and potential therapeutic target in respiratory diseases with type-2 airway inflammation, including severe asthma." (PMID 34093589, 2021). "Nevertheless, taking into account the impressive results with anti-TSLP therapy in severe asthma, one may expect that in such case combined anti-IL-33 and anti-TSLP therapy could be even more beneficial." (PMID 34084159, 2021). "The meta-analysis identified as the 5 most significant loci on chromosomes 17q12-21 near PGAP3 and ERBB2, 6p21.32 near HLA-122 DRB1/-DQA1, 5q22.1 near TSLP, 2q12 near IL1RL1/IL18R, and 9p24.1 near IL33 in both the whole sample and in the subset that included only subjects with early-onset asthma." (PMID 33673725, 2021). "Our results suggest that a c-Rel-specific inhibitor such as the IT-603 and IT-901 compounds may offer a novel therapeutic strategy to inhibit IL-33-induced ILC2 activity in diseases such as asthma and allergies." (PMID 34194431, 2021). "Antibodies to IL-33 are evaluated in ongoing asthma-related clinical studies." (PMID 34254951, 2021). "Interleukin (IL)−33, a cytokine of the IL-1 family, was found to play an important role in the pathogenesis of allergic diseases, i.e., AD, asthma, allergic rhinitis, urticaria, and allergic conjunctivitis, and targeting the IL-33 inflammatory axis has therapeutic potential in controlling AD." (PMID 34561424, 2021). "This has implications for the targeting of the IL-33/IL1RL1 axis inhibitors to a subset of patients of a specific genotype likely to gain the greatest clinical benefit and is highly relevant, with multiple pharmaceutical companies developing anti–IL-33/IL1RL1 approaches for the treatment of asthma." (PMID 32324168, 2020). "In addition, the expression of TSLP and IL-33 is enhanced in the peripheral blood and lung tissue of patients with severe asthma." (PMID 32397396, 2020). "IL-33 deficiency decreased CD146 expression and alleviated asthma severity." (PMID 32793232, 2020). "Reduce airway hyperresponsiveness, airway wall remodeling and goblet cells hyperplasia, suppressed pulmonary eosinophilia and asthma-related cytokines IL-4 and IL-33, altered the microbial community structure and the short chain fatty acids content in the gut of the asthmatic mice." (PMID 32158441, 2020). "IL-33 is mainly secreted by the airway epithelium and evidenced to exacerbate the Th2-mediated inflammation via further promoting the secretion of IL-4, IL-5, and IL-13 in allergic patients with asthma." (PMID 32650472, 2020). "The largest number of ST2 expressed moDCs in asthma may suggest the important effect of epithelial derived IL-33 on DCs response in this disease." (PMID 32842623, 2020). "Additionally, IL-33, a cytokine for which a major role was demonstrated in fungus- and virus-induced asthma exacerbations in mouse models but also in moderate asthmatic patients, is a target under investigation." (PMID 32296705, 2020). "Targeting the IL-33/ST2 axis in allergic diseases including asthma may be beneficial by decreasing eosinophil production in the bone marrow." (PMID 32466530, 2020). "Collectively, our results establish SERPINA3I as a regulator of IL-33 in the lungs following exposure to the bacterial allergen SplD, and that the asthma phenotypes of mouse strains may be strongly influenced by the observed frameshift mutation in Serpina3i." (PMID 33072128, 2020).
asthma (continued). "In addition, IL-33 induced angiogenesis and vascular permeability, as demonstrated in a study of a murine asthma surrogate." (PMID 33308251, 2020). "It was shown recently that IL-33 is an important asthma exacerbation mediator." (PMID 32702053, 2020). "MK2 and 3 are kinases activated by p38α; MK2/3 inhibitors or knockout of MK2/3 in mice reduced the production of IL-6 and IL-13 (two cytokines implicated in asthma) but not IL-5, IL-9 or GM-CSF in response to IL-33." (PMID 32103032, 2020). "The epithelium controls the local respiratory immune activities that are also mediated by thymic stromal lymphopoietin, IL-25 and IL-33, which might lead to a Th2 type inflammation, thus facilitating the development of asthma." (PMID 32158441, 2020). "A GWAS also identified IL33 as being potentially important in asthma." (PMID 32349347, 2020). "The study aimed to evaluate the expression of TSLP, IL-33, and IL-17A in human monocyte derived dendritic cells (moDCs) co-cultured with respiratory epithelium and monocyte derived macrophages (moMφs) in asthma, chronic obstructive pulmonary disease (COPD) and healthy controls." (PMID 32842623, 2020). "The effect of antibody drugs against IL-33 could be examined through clinical trials for asthma and other diseases." (PMID 33308251, 2020). "Indeed, IL-33 responsive TH cells have been reported in several studies of allergic diseases including asthma." (PMID 32466530, 2020). "Both IL-33 and ILC2s are critically involved in the early stages of asthma exacerbation." (PMID 33597946, 2020). "HpBARI binds and blocks ST2, inhibiting IL-33 responses in a murine model of asthma." (PMID 32420871, 2020). "IL-33 and its receptor, ST2, are both also genetically linked to asthma." (PMID 32326950, 2020). "Moreover, there is evidence that demonstrates a link between the production of IL-33 during the perinatal period and the development of asthma." (PMID 32397226, 2020). "Furthermore, epithelial cell-derived cytokines such as IL-33 and IL-25 (also known as alarmins) can play major role in the initiation of Th2-high asthma." (PMID 32477356, 2020). "Another anti-IL-33 monoclonal antibody, Etokimab (AnaptysBio), is also under evaluation or completed Phase2a trials for moderate-to-severe adult atopic dermatitis, chronic rhinosinusitis with nasal polyps, asthma and peanut allergy." (PMID 32754154, 2020). "The increased expression of IL-33 in airway epithelial cells is closely related to the severity of asthma, and IL-33 has been shown to not only exacerbate airway inflammation but also promote airway remodeling in asthma." (PMID 32793232, 2020). "This gives a possible mechanism linking IL-33 and ILC2s to future asthma after RSV infection." (PMID 30941335, 2019). "In addition to IL-17, some cytokines, including thymic stromal lymphopoietin (TSLP), IL-33 and IL-25, are key factors for the development of allergic diseases, such as asthma and skin atopic dermatitis, that act by promoting Th2-type responses." (PMID 31805177, 2019). "However, during prolonged chronic inflammation, such as asthma, the expression of IL-33 is increased in both epithelial cells and airway smooth muscle cells, two compartments of the asthmatic lung that are associated with increased mast cell numbers." (PMID 31275312, 2019). "Notably, IL-33 and ST2/IL1RL1 (IL-33 receptor) genes are considered to be asthma disease susceptibility genes and have been identified in genome-wide association studies." (PMID 31616416, 2019). "Another source of IL-33 in the airways of asthma patients are the smooth muscle cells." (PMID 31191511, 2019). "The Der p-induced asthma model was associated with increased AHR and bronchial wall thickening, elevated serum IL-19, IL-13, IgE levels, BALF IgA levels, increased immune cell infiltration, and tissue IL-33 and CCL11 in the lungs." (PMID 31114590, 2019).
asthma (continued). "Moreover, IL-33 expression was higher in lung samples from patients with severe asthma than in those with mild asthma and IL-33 expression was mainly localized to epithelial and endothelial cells, neutrophils, fibroblast and mast cells." (PMID 31191511, 2019). "ST2 and IL-33 blocking antibodies showed to be effective in asthma and atopic dermatitis." (PMID 31736655, 2019). "Consistent with the proposed role of IL-33 in asthma, earlier studies showed that blockade of IL-33 or its cell surface receptor ST2 clearly reduces disease severity, as evidenced by reduced Th2 cytokine production, airway inflammation, airway hyperresponsiveness, and mucus production." (PMID 31197082, 2019). "Thus, this leads to the concept that IL-33 plays a crucial role in modulating immune cells functioning in several conditions such as asthma and lung diseases." (PMID 31766607, 2019). "Moreover, DAPP1 expression in the lung was highly positively correlated with a panel of pro-inflammatory cytokines, including several that have been implicated in asthma, such as IL1A, IL7, IL12A, IL17A, IL23A, and IL33." (PMID 31869344, 2019). "To prove this hypothesis, we treated intranasally wild type and NIP45−/− mice with recombinant IL-33 in our murine model of asthma." (PMID 31666531, 2019). "They noticed that IL-33 was significantly increased by rhinovirus infection, thus suggesting that IL-33 inhibition could be a new successful therapy for asthma." (PMID 31766607, 2019). "Genome-wide association studies show that both IL-33 and ST2 are associated with asthma." (PMID 31455422, 2019). "Serum IL-33 level in asthma significantly increases with the development of the disease." (PMID 30846811, 2019). "IL-33 can induce type 2 immune responses, such as allergic inflammation and asthma." (PMID 31509992, 2019). "Several mechanisms in which IL-33 participates in the development of asthma have been described." (PMID 31057533, 2019). "cGAMP stimulated lung fibroblast cells to produce IL-33 in vitro, and mice deficient for IL-33 or IL-33 receptor (ST2) failed to develop asthma enhancement by cGAMP." (PMID 31616416, 2019). "The exact role of androgens such as testosterone in asthma still needs further investigation since testosterone is able to induce IL-33 mRNA in mast cells, however, lower levels of IL-33 and TSLP have been detected in the bronchoalveolar lavage of Alternaria challenged mice." (PMID 31231357, 2019). "On the other hand, recent advances in the immunoreactions of asthma revealed that in the innate immune response, epithelial cells release innate immune molecules such as IL-33, TSLA, and so forth in response to foreign stimulants such as microorganisms, dust, smoke, and so forth." (PMID 30965592, 2019). "IL-33 plays an important role in the pathology of asthma and the TH2 cell differentiation in vivo." (PMID 30949175, 2019). "IL-33 administration in the airways of mice enhances TH2-associated cytokine production in the lungs, increases mucus production and causes a severe type 2 airway hyper-reactivity that mimics the pathophysiology of asthma." (PMID 30949175, 2019). "A central function of IL-33 in the pathogenesis of asthma has been reported." (PMID 29686383, 2018). "Moreover, IL-33 levels correlate with clinical asthma severity, and IL-33 or its receptor (ST2) gene polymorphic variants have been implicated in susceptibility to allergic rhinitis and the risk of asthma." (PMID 30713536, 2018). "Collectively, these results from asthma-induced human samples correlate with our findings obtained using mouse models, showing that IL-33-induced upregulation in the expression of IRAK-M is associated with upregulation of proinflammatory IRAK-M dependent genes." (PMID 29686383, 2018).
asthma (continued). "Their subsequent experiments revealed that IL-33 polarizes microglia and macrophages toward an anti-inflammatory M2 phenotype, a well-recognized mechanism of IL-33 action in several immune-mediated diseases including spinal cord injury, asthma, and EAE." (PMID 30515150, 2018). "Furthermore, EBC IL-33 levels correlated positively with blood eosinophil numbers and percentages, not only in asthma but also in COPD." (PMID 29859068, 2018). "Elevated IL-33 stimulates systemic T-helper 2 (Th2) type of inflammation and contributes to allergen-induced airway inflammation and hyper-responsiveness, aggravating asthma symptoms." (PMID 30257479, 2018). "Our results provide strong evidence in an independent sample that this PTV protects against asthma and suggests that knocking down IL33 function may be a useful therapeutic approach for asthma." (PMID 29691392, 2018). "Recognition of the powerful effects of IL-25, IL-33, and TSLP produced by respiratory epithelial cells is an important new element in understanding the potential for respiratory viruses to cause and/or exacerbate asthma." (PMID 29915592, 2018). "Thus, IL-33 is involved in regulation of type 2 inflammation that is known to be the dominant mechanism in asthma." (PMID 30544846, 2018). "Moreover, in all these studies, which included thousands of patients from diverse ethnic groups and different forms of asthma, IL33 and ST2/ILRL1 were the only two genes reproducibly found to be associated with asthma." (PMID 29977243, 2018). "In another study, cockroach extract-induced IL-33 expression dampened antiviral immunity to subsequent PVM infection, providing a mechanism which could predispose asthma patients to more symptomatic viral infections." (PMID 30513770, 2018). "Therefore, it is plausible to explore the potential of IL-33 axis as an immunotherapeutic target in the initiation, progression, and treatment of asthma." (PMID 30105028, 2018). "We had also shown that HDAC3 was a key epigenetic regulator of IL-33 in animal models of asthma." (PMID 30562364, 2018). "IL-33 is considered as one of the most critical molecules in asthma pathogenesis." (PMID 29977243, 2018). "Moreover, intranasal administration of PGE2 prevented ILC2 accumulation in the lung and attenuated airway inflammation in an asthma model induced IL-33." (PMID 29593738, 2018). "In patients with asthma, IL-33 levels were elevated and correlated with disease severity." (PMID 30213101, 2018). "We therefore examined whether asthma-associated pLOF variants in GSDMB and IL33 associate with a lower risk of other atopic disorders in UK Biobank." (PMID 29691411, 2018). "IL-33 is strongly involved in the pathogenesis of asthma, anaphylaxis, allergy and dermatitis, and genetic variations in IL33 locus are associated with increased susceptibility to asthma." (PMID 30544846, 2018). "The G allele of the polymorphism of the IL33 gene, rs12551256, showed a negative correlation with asthma, whereas the A IL1RL1 gene allele, rs1041973, correlated with the production of IL-5 in the serum, sIgE levels, and positive scores of skin prick tests." (PMID 30304837, 2018). "Importantly, recent studies have demonstrated that IL-33 has the ability to directly stimulate mast cells and enhance the Th17 response during the pathogenesis of asthma." (PMID 30112116, 2018). "Significantly, production of IL-5 and IL-13 is 100- to 200-fold greater in ILC2 cells compared to CD4+ T cells suggesting that IL-33-dependent activation of ILC2 cells during RV infection could play a major role in the development of asthma." (PMID 29915592, 2018). "Thus, IL-33 production induces IL-5 and IL-13 release in asthma, cytokines that are produced by Th2 and ILC2 cells." (PMID 28262704, 2017). "Furthermore, polymorphisms in the genes for IL-33, its receptor ST2, and the downstream signaling have been associated with asthma development and severity in genome wide association studies." (PMID 28652606, 2017).
asthma (continued). "These include the genes IL33 and IL1RL1, and sequence variants in the human genome close to these genes were initially found to affect the number of eosinophils, cells that play a role in inflammation of the airways in asthma." (PMID 28273074, 2017). "However, in mouse models of asthma, IL-33 signaling to IL-33R+Foxp3+ Treg cells results in their expression of Th2 cytokines, and abrogation of suppressive ability." (PMID 29045903, 2017). "Our study provides a plausible explanation of why a great number of AD patients develop asthma and other allergic disorders later in life, suggesting that IL-33 may be a promising target in the prevention of allergic diseases." (PMID 28490737, 2017). "Further studies are needed to determine whether targeting IL-33 can treat AD, and whether clinical control of AD with IL-33 blockade will lower the incidence of asthma." (PMID 28490737, 2017). "Collectively, these findings show that IL-33 aggravates important features of antigen-driven asthma, which may have implications for asthma exacerbations." (PMID 28652606, 2017). "Since ILC2s have been detected in airway tissues, thus we hypothesize that the augmented Th2-cytokines in nasal tissue from CRS patients with asthma may be derived from sinonasal tract ILC2s in response to enhanced IL-25, IL-33 and TSLP release." (PMID 28199345, 2017). "However, ST2/IL-33 signaling can also lead to progression of various lung and skin diseases such as asthma and AD." (PMID 28484466, 2017). "This study investigated the potential of IL-33 to exacerbate antigen driven asthma responses." (PMID 28652606, 2017). "Furthermore, IL-25 and IL-33 levels were enhanced in asthma during innate immune response to allergens, and they play important roles at the onset of allergic inflammation in asthma." (PMID 29283409, 2017). "IL-33 is upregulated in the airways during HRV-induced asthma exacerbations." (PMID 26810609, 2016). "In a mouse model of asthma, MWCNTs induced an influx of inflammatory cells, increased mucus and IgG1 production, and increased the activation of inflammatory genes IL-13, Il-25, IL-33 and GM-CSF." (PMID 26999172, 2016). "Given the function of OSM in activating stromal cells and elevation of OSM levels in IPF and severe asthma, putative regulation of IL-33 may be of importance in the modulation of innate immunity, chronic inflammation, and tissue repair in lung disease." (PMID 27703303, 2016). "IL-33 signaling is a key driver of type 2 immunity, which favors protective immune responses in parasite infections and tissue repair but is also involved in pathological conditions, such as asthma, allergy, and eosinophilia." (PMID 27148268, 2016). "In this context, IL-33 functions as a prototypical ‘alarmin’ and an endogenous ‘danger’ signal to alert the immune system after epithelial cell damage during trauma or infection and plays an essential role in pro-inflammatory pathway in asthma." (PMID 27658857, 2016). "Genetic ablation of IL-33 results in less ovalbumin (OVA)-induced airway inflammation associated with less M2 macrophage differentiation, suggesting the importance of M2 macrophages in asthma." (PMID 27007158, 2016). "Interestingly, it was shown that asthma patients have increased expression of IL-25, IL-33, and TSLP in the lungs." (PMID 26965110, 2016). "While ST2/IL-33 signaling is important for TH2 immune response to tissue repair and helminth infection, it has been associated with immunity-related diseases including asthma, allergy, cardiovascular disease, central nervous system disease, pain and arthritis." (PMID 26735493, 2016). "Furthermore, genetic variants of TSLP, IL-17RB, IL-33, and ST2 have been associated with increased susceptibility to asthma." (PMID 26965110, 2016). "In addition, genes discovered in genome-wide association studies of asthma (RORα, IL-13, IL-33, IL-1RL1; which are all related to ILC2) suggest a key role for ILC2 in asthma." (PMID 26727464, 2016).